LEP (leptin)
Diseases named in the same sentence as LEP in open-access papers (continued):
Sharing a sentence is not in itself a finding about the gene and the disease.
Obesity (continued). "It positively correlates with BMI; however, obesity is considered a state of reduced leptin function." (PMID 31178685, 2019). "Compelling evidence has suggested that the hyperleptinemic condition (increased plasma leptin concentration) in obesity is one of important factors contributing to the hyper-activated SNS which eventually leads to many cardiovascular complications." (PMID 31682617, 2019). "Insulin resistance is a defining characteristic of T2DM and patients with obesity are often leptin resistant." (PMID 31601900, 2019). "Leptin levels are elevated in obesity, but leptin’s insulin sensitizing and anorexigenic effects are abrogated, due to resistance of target cells to the action of this hormone in this condition." (PMID 30823446, 2019). "This attracted a lot of interest toward the clinical use of leptin for the treatment of obesity in humans." (PMID 31717265, 2019). "Therapy with adiponectin administration has shown to improve insulin resistance in animal models of obesity; however, in lipodystrophic animal cases, the complete reversal of insulin resistance requires the co-administration of leptin." (PMID 31178685, 2019). "The adipose tissue is a source of several hormones of which the adipokines - leptin, adiponectin, resistin, and omentin - play important roles in the pathophysiology of obesity and diabetes in humans." (PMID 31533709, 2019). "In adulthood, Nnat null mutants have lower energy expenditure and are hypoactive, leptin resistant and hyperphagic, which together lead to the development of obesity." (PMID 31270580, 2019). "We, therefore, proposed that defining the role of astrocytes on leptin signaling would provide an understanding of the central mechanisms involved in the sympathetic over-activation exhibited during HFD-induced obesity." (PMID 31803004, 2019). "We evaluated the association between MPS-1 and prognosis and circulating leptin level of CRC patients, especially in the context of obesity." (PMID 31506433, 2019). "In a diet-induced obesity and leptin resistance mouse model, increased leptin levels are found in the hippocampus." (PMID 31324021, 2019). "Leptin is an adipose-derived hormone that links to sympathetic activation in obesity-related hypertension." (PMID 31803004, 2019). "Leptin levels are increased during obesity but leptin signaling in the hypothalamus is impaired, a phenomenon called central leptin resistance." (PMID 31920961, 2019). "Apart from the role of leptin in obesity, it is involved in developing other disorders such as type 1 diabetes, systemic lupus erythematosus and psoriasis." (PMID 30806766, 2019). "These cells are altered by obesity (obASCs) and previous studies have shown that obASCs secrete higher levels of leptin." (PMID 30897853, 2019). "This leptin-dependent increase in Actinobacteria in Hets was due mostly to Coriobacteriaceae (family), also from days 7 to 35, suggesting this microbial family is influenced by leptin or obesity status during HFD." (PMID 31882890, 2019). "Overall, the contribution of WHR and CRP to the metabolic profile shows that beyond increased whole-body fat mass (measured by BMI and leptin), visceral adipose tissue and related systemic inflammation play a role in obesity-related GMV reductions." (PMID 31427957, 2019). "Another feature of obesity is increased leptin secretion that appears to be functionally connected with the HPA axis in humans." (PMID 31440490, 2019). "Circulating leptin concentrations are often high in individuals with obesity, thus suggesting a state of leptin resistance." (PMID 31877943, 2019). "Studies indicated that leptin in the hypothalamus mediates the anti-obesity actions and activation of the sympathetic nervous system (SNS) to induce lipolysis in white adipose tissue and thermogenesis in brown adipose tissue." (PMID 31052312, 2019).
Obesity (continued). "In conclusion, ginsenoside Rb1 exerts significant anti-obesity, anti-hyperglycemic, and anti-diabetic effects by regulating the effects of glycolipid metabolism and improving insulin and leptin sensitivities." (PMID 30823412, 2019). "Obesity affected the periodontal conditions, the alveolar bone pattern, and the salivary leptin concentration." (PMID 30758470, 2019). "Many “in vivo” studies have attempted to define the role of obesity and leptin in impacting breast cancer." (PMID 30634494, 2019). "In the present investigation, the polygenic FATZO mouse model of obesity and type 2 diabetes with an intact leptin pathway diet developed progressive NAFLD/NASH similar to humans when fed with WDF." (PMID 30885145, 2019). "Leptin is an adipocyte-derived hormone that is up-regulated in obesity and plays a central role in regulating energy homeostasis." (PMID 31506433, 2019). "The relative abundance of Parabacteroides was negatively correlated with body weight gain (P<0.05), hepatic triglyceride content (P<0.05), epididymal fat (P<0.05), ALT (P<0.05) and leptin (P<0.05) plasma levels in our early obesity and NAFLD model." (PMID 30971408, 2019). "This is primarily because DGAT1 mouse knockout (KO) models are resistant to diet-induced obesity, show decreased levels of tissue triglycerides, and have increased sensitivity to insulin and leptin." (PMID 31345219, 2019). "In genetically-induced obese mice (ob/ob) which cannot synthesize leptin, treatment with recombinant leptin is highly effective at decreasing appetite and reversing obesity." (PMID 31739649, 2019). "Adiponectin and leptin are adipokines produced from adipose tissue, and are related to thinness and obesity, respectively." (PMID 31324858, 2019). "Understanding the inflammatory effects of leptin on the pulmonary system provides opportunities to develop strategies against lung injury related to metabolic syndrome or obesity." (PMID 30832310, 2019). "Altering levels of the adipokines, mainly adiponectin and leptin, has been shown to improve energy homeostasis and offset diet-induced obesity." (PMID 31182642, 2019). "Analogous to insulin resistance, inflammatory processes in the brain, specifically in hypothalamic neurons, would provide a link between obesity and the relatively newly coined term leptin resistance." (PMID 31225498, 2019). "In conclusion, in male patients with obesity, the combination of leptin resistance in the hypothalamus and a preserved leptin sensitivity in the testis leads to hypogonadism." (PMID 31817436, 2019). "The effect of excess leptin on Leydig cells is suppression of testosterone production; thus, elevated leptin in adolescents with obesity contributes to hypogonadism." (PMID 31052376, 2019). "Adipocytokines, such as tumor necrosis factor (TNF)-α, plasminogen activator inhibitor (PAI)-1, monocyte chemoattractant protein (MCP)-1, leptin, and adiponectin, play critical roles in obesity-related diseases." (PMID 31648235, 2019). "The exact mechanisms via which obesity induces defects in NK cells are now emerging, several studies showed that leptin, an adipokine elevated in obese adults and children, can modulate NK cell functions." (PMID 31018563, 2019). "The present findings seem to be consistent with the findings of other studies, which discovered that impairment in leptin signaling was commonly found among people with diet-induced obesity." (PMID 31871451, 2019). "In fact, the leptin sensitizers, such as celastrol and withaferin, have been reported to show both anti-diabetic and anti-obesity effects in mice." (PMID 31509948, 2019). "We analyzed serum IGF-1, leptin, and adiponectin levels to see the relationship and its possible role in the development of obesity." (PMID 31488172, 2019). "The reason is that increased fat mass would lead to increased leptin production, and since obesity induces precocious puberty, leptin has been considered as a metabolic signal to the reproductive system." (PMID 31379735, 2019).
Obesity (continued). "In the EPI depot, melatonin reversed the increase of leptin, Il-6, Mcp-1 and Tnf-α triggered by obesity." (PMID 31489938, 2019). "Rats orally supplemented with physiological doses of leptin during lactation-suckling were protected against the age-related increase in BW and adiposity and were more resistant to obesity and related complications when exposed to a HF diet in adulthood." (PMID 31817318, 2019). "Females secrete more leptin than males and this difference in leptin secretion is intensified with obesity." (PMID 31766143, 2019). "Unlike monogenic leptin deficient ob/ob or db/db mice, the FATZO mice area polygenic model of obesity and type 2 diabetes when fed regular rodent diet, with an intact leptin pathway, thereby making it more translatable to the human disease." (PMID 30885145, 2019). "Obesity and diabetes have many common pathological characteristics: insulin resistance (hyperinsulinemia), abnormal fat metabolism (elevated leptin, decreased adiponectin), hyperglycemia, hyperlipidemia and chronic inflammation." (PMID 31440472, 2019). "Both Friedman and Leibel have had highly successful careers and continued to conduct important research on obesity and leptin biology, albeit with different emphases and directions." (PMID 30357355, 2019). "The first one concerned an Egyptian two-year-old homozygous patient with a very low serum Leptin level and a severe early onset obesity, in which the genetic analysis was performed by the sequencing." (PMID 31871931, 2019). "Leptin, which is augmented in obesity, also up-regulates pro-inflammatory cytokines, such as TNF-α and IL-6, which are associated with insulin resistance and the development of type II diabetes." (PMID 31357412, 2019). "Obesity leads to chronic inflammation and changes the secretion patterns of adipokines, such as leptin in adipose tissue." (PMID 31739649, 2019). "This showed that leptin decreased high fat diet-induced obese mice body weight and inhibited the Hh signaling pathway, which suggested that leptin and the Hh signaling pathway have an important role in obesity." (PMID 31022919, 2019). "In obesity, increases in white adipose tissue accumulation and leptin levels are accompanied by hypothalamic resistance to leptin." (PMID 31920961, 2019). "It has been also established that Mitogen activated kinase 1/2 (MEK 1/2)/ERK pathways plays an important role in the anti-obesity and cell differentiation effect of leptin." (PMID 31847355, 2019). "This study provides further insights into the potential roles of E2 and leptin in HFD-induced obesity and gut microbiota." (PMID 31882890, 2019). "Nevertheless, these data show that human adipose tissue undergoes neuropathy with obesity (likely the leptin-resistant form) similar to the mouse model (leptin-deficient)." (PMID 31509546, 2019). "The resultant insulin and leptin resistance would likely result in unfavorable energy intake and expenditure and favor the development of obesity." (PMID 31141526, 2019). "Considering the anorectic activity of leptin, propolis has potential to attenuate feeding and subsequently preventing obesity." (PMID 31805752, 2019). "We explored the effects of Roux-en-Y gastric bypass (RYGB) on the circulating levels of adiponectin, leptin, and the adiponectin/leptin (Adpn/Lep) ratio in patients with obesity and type 2 diabetes (T2D)." (PMID 31484347, 2019). "Blockade of CB1 activation attenuates obesity by affecting multiple areas including leptin signaling, white adipose tissue browning, gut microbiota interactions, and reducing inflammation." (PMID 31134094, 2019). "Current knowledge on the pathophysiology of obesity involves altered signaling to the brain from adiposity hormones, such as leptin and insulin, resulting in hyperphagia and positive energy balance." (PMID 31878078, 2019).
Obesity (continued). "This reduction in leptin levels leads to increased appetite while reducing energy expenditure and therefore promotes the development of obesity and other metabolic disorders." (PMID 31671606, 2019). "Based on these findings it seems promising to test if intranasal leptin overcomes leptin resistance in patients with obesity and type 2 diabetes." (PMID 31222048, 2019). "The results of these studies provide evidence on a cellular level of obesity-mediated promotion of TNBC metastasis via increased levels of leptin produced by obesity-altered ASCs." (PMID 31118047, 2019). "Development of leptin resistance, and also cytokine resistance in obesity provided new insights for development of obesity, as well as a potential therapeutic avenue." (PMID 31488870, 2019). "This inactivation resulted in insulin resistance at the central nervous system (CNS) but mice also developed obesity, combined with hyperphagia, an increase of leptin and insulin concentrations in plasma, as well as the development of hypertriglyceridemia." (PMID 31551756, 2019). "Most studies investigating leptin in the context of obesity have focused on breast cancer, where leptin can directly stimulate the proliferation of breast tumour cells." (PMID 31018563, 2019). "Accounting for the role of obesity and leptin in breast cancer, several possible mechanisms have been suggested to potentially mediate drug resistance in tumor cells." (PMID 31380268, 2019). "Biochemical and genetic evidence in mice suggests this leptin-induced inhibitor of leptin signaling limits the ability of high leptin levels to prevent obesity." (PMID 30357355, 2019). "A large number of studies demonstrated that the JAK2 / STAT3 pathway is essential for the anti-obesity effects of leptin." (PMID 31847355, 2019). "Among the adipokines leptin, whose synthesis and plasma levels increase in proportion to fat mass, has emerged as a key molecule linking obesity to breast cancer." (PMID 31336913, 2019). "While obesity and a high fat diet appear to promote exacerbated lung disease, there is some debate over how T cells are affected by leptin." (PMID 30978945, 2019). "Leptin is an anti-obesity hormone, its concentration in the blood is elevated in people with obesity, however individuals become resistant to its satiety and weight-reducing effect." (PMID 31467596, 2019). "Two studies on Tunisian populations found a link between the common LEP −2548G/A genotype and obesity." (PMID 31871931, 2019). "The authors clearly show that the local signaling of leptin in bone marrow stromal precursors, during obesity, is essential for the adipocyte commitment and differentiation." (PMID 31920961, 2019). "Decreased sensitivity and response to leptin action results in the development of leptin resistance leading to hyperleptinemia, which occurs mostly during the early stages of obesity and which is closely related to the onset of insulin resistance." (PMID 31215461, 2019). "Sulphoraphane has been shown to help reduce obesity, improve glucose tolerance, and restore leptin sensitivity in high fat-sucrose diet fed obese mice." (PMID 30778334, 2019). "High leptin levels and leptin:adiponectin ratio are predictors of obesity related complications as type 2 diabetes mellitus (T2DM) and hypertension independent of BMI or the metabolic syndrome (MetS) criteria." (PMID 31189474, 2019). "It has been demonstrated that glycosphingolipids-derived gangliosides take part in central leptin signaling and its neuronal deletion induces obesity in mice." (PMID 30406389, 2019). "Following the discovery of leptin and ghrelin in the 1990s, vigorous research on obesity has been conducted." (PMID 31798010, 2019). "This study shows the possibility of using psoriasin, nestin, Krt16, and IL-21 as biochemical markers of psoriasis and highlights the correlation of these with biomarkers of obesity (BMI, leptin, and resistin)." (PMID 31275060, 2019).
Obesity (continued). "The relationship between obesity and colorectal cancer development can be attributed to metabolic syndrome and expression of various adipokines (leptin and adiponectin) which drive colorectal cancer development." (PMID 31245287, 2019). "The failure of leptin to restore metabolic homeostasis in obesity is described as state of leptin resistance." (PMID 30915034, 2019). "Leptin was firstly described as an anti-obesity hormone, but several actions of leptin in CNS have been reported." (PMID 30949073, 2019). "Reduced secretion of adiponectin, resulting in low serum concentrations, is a common feature of obesity, whereas low serum leptin is used as an indicator of malnutrition." (PMID 31182642, 2019). "Obesity leads to high circulating concentrations of different hormones, such as insulin and leptin and low levels of the hormone adiponectin, all factors which have been described to increase the risk of advanced PCa." (PMID 31284686, 2019). "In obesity, leptin levels are increased, but the activity of leptin is decreased due to leptin resistance." (PMID 31438590, 2019). "Among three markers altered by obesity [leptin, adiponectin and soluble TNF receptor 2 (sTNF-R2)], plasma levels of sTNF-R2 and leptin showed independent positive association with breast cancer risk." (PMID 31555578, 2019). "In a pregnancy complicated by obesity, circulating leptin concentrations are higher than normal, and circulating adiponectin concentrations are slightly lower than normal throughout pregnancy." (PMID 30732639, 2019). "Some studies sustain the correlation of the high levels of circulatory leptin with diet obesity and an improvement of leptin level was observed after a balanced distribution in the dietary pattern." (PMID 30605486, 2019). "Obesity affects the periodontal conditions, the alveolar bone pattern, and the salivary leptin concentration." (PMID 30758470, 2019). "As these signaling pathways are blunted in obesity, further research efforts have been made to discover therapeutic agents to improve leptin sensitivity focusing on JAK-STAT and PI3K-Akt-FoxO1." (PMID 30935076, 2019). "Altogether, the results of this study provide a molecular mechanism for the inflammatory effect of leptin in the lung and suggest that leptin functions as a link between obesity and lung inflammation." (PMID 30832310, 2019). "Leptin—an adipose tissue hormone correlates with the amount of body fat, therefore, obesity is accompanied with hyperleptinemia as also observed in our study." (PMID 31480394, 2019). "How can we reconcile the apparent discrepancies between our results and previous reports, mostly based on radioactive tracer studies, which suggest diminished leptin BBB transport in a state of obesity ?" (PMID 30283080, 2019). "The objective was to establish if psoriasin, nestin, Krt16, and IL-21 were possible biomarkers of psoriasis and to correlate them with Body Mass Index (BMI), leptin, and resistin (biomarkers of obesity)." (PMID 31275060, 2019). "Obesity is accompanied by a dysregulation in leptin signaling where hyperleptinemia and leptin resistance are evident." (PMID 30707678, 2019). "Ornithine, previously shown to be associated with hepatic damage, was found to be associated with leptin and ALT, providing a further evidence of its association with obesity associated non-alcoholic fatty liver disease." (PMID 31640727, 2019). "Literature has been focused on the role of leptin in determining obesity and related diseases in humans." (PMID 31091785, 2019). "In contrast to leptin, adiponectin is down-regulated in obesity, and the circulating adiponectin levels are inversely correlated with body fat amount." (PMID 31398785, 2019). "In this study, we used less aggressive, basal-A TNBC-established cell lines and a luminal ER+ cell line MCF7 for comparison and observed that obesity-altered ASCs promoted a more aggressive metastatic phenotype in these cells through leptin-mediated pathways." (PMID 31118047, 2019).